H4C13 (H4 clustered histone 13)
Description:
Core component of nucleosome. Nucleosomes wrap and compact DNA into chromatin, limiting DNA accessibility to the cellular machineries which require DNA as a template. Histones thereby play a central role in transcription regulation, DNA repair, DNA replication and chromosomal stability. DNA accessibility is regulated via a complex set of post-translational modifications of histones, also called histone code, and nucleosome remodeling.
Synonyms: H4/K; H4FK; HIST1H4L; H4.k
Target class: Other nuclear protein
Gene: Protein-coding gene on chromosome 6 (27,873,148 to 27,873,534, reverse strand). Ensembl gene ENSG00000275126.
Subcellular location: Nucleus; Chromosome
Pathways (Reactome):
Gene expression (Transcription): B-WICH complex positively regulates rRNA expression; DNA methylation; ERCC6 (CSB) and EHMT2 (G9a) positively regulate rRNA expression; MLL4 and MLL3 complexes regulate expression of PPARG target genes in adipogenesis and hepatic steatosis; NoRC negatively regulates rRNA expression; PRC2 methylates histones and DNA; RNA Polymerase I Promoter Escape; RNA Polymerase I Promoter Opening; RUNX1 regulates genes involved in megakaryocyte differentiation and platelet function; RUNX1 regulates transcription of genes involved in differentiation of HSCs; Regulation of endogenous retroelements by KRAB-ZFP proteins; Regulation of endogenous retroelements by Piwi-interacting RNAs (piRNAs); Regulation of endogenous retroelements by the Human Silencing Hub (HUSH) complex; SIRT1 negatively regulates rRNA expression; Transcriptional regulation by small RNAs
Chromatin organization: CHD1 and CHD2 subfamily; CHD6, CHD7, CHD8, CHD9 subfamily; ChAHP complex assembly; HATs acetylate histones; HDACs deacetylate histones; HDMs demethylate histones; Interaction of NuRD complexes with transcription factors; NuRD complex assembly; PKMTs methylate histone lysines; RMTs methylate histone arginines
DNA Repair: Cleavage of the damaged purine; Cleavage of the damaged pyrimidine; Nonhomologous End-Joining (NHEJ); Processing of DNA double-strand break ends; Recognition and association of DNA glycosylase with site containing an affected purine; Recognition and association of DNA glycosylase with site containing an affected pyrimidine; Recruitment and ATM-mediated phosphorylation of repair and signaling proteins at DNA double strand breaks
Cell Cycle: Condensation of Prophase Chromosomes; Deposition of new CENPA-containing nucleosomes at the centromere; G2/M DNA damage checkpoint; Inhibition of DNA recombination at telomere; Packaging Of Telomere Ends
Developmental Biology: Activation of anterior HOX genes in hindbrain development during early embryogenesis; Chromatin modifications during the maternal to zygotic transition (MZT); Replacement of protamines by nucleosomes in the male pronucleus
and 20 more pathways
Gene Ontology:
Molecular function: protein binding; RNA binding; structural constituent of chromatin; DNA binding; protein heterodimerization activity
Biological process: negative regulation of megakaryocyte differentiation; nucleosome assembly; chromatin organization; protein localization to CENP-A containing chromatin; telomere organization
Cellular component: CENP-A containing nucleosome; chromosome, telomeric region; extracellular exosome; membrane; nucleoplasm; nucleosome; nucleus; protein-containing complex; extracellular region; chromosome
Genetic constraint (gnomAD): Loss-of-function variants: 12 observed, 5.86 expected, observed/expected ratio (o/e) 2.05. That is too few expected variants to judge how well the gene tolerates losing a copy. Missense variants: 171 observed, 160.04 expected, observed/expected ratio (o/e) 1.07, 90% interval 0.94 to 1.21. Synonymous variants: 94 observed, 64.3 expected, observed/expected ratio (o/e) 1.46, 90% interval 1.24 to 1.73.
Homologues: Paralogues in human: H4C1 (100% identical), H4C11 (100% identical), H4C12 (100% identical), H4C14 (100% identical), H4C15 (100% identical), H4C16 (100% identical), H4C2 (100% identical), H4C3 (100% identical), H4C4 (100% identical), H4C5 (100% identical), H4C6 (100% identical), H4C8 (100% identical), and 2 more.
Diseases named in the same sentence as H4C13 in open-access papers:
H4C13 is named in the same sentence as 3 diseases in open-access papers, as found by Europe PMC text mining. Sharing a sentence is not in itself a finding about the gene and the disease. The quoted sentences say what the papers report.
bipolar disorder (1 paper, 2021). A disorder of the brain that causes unusual shifts in mood, energy, activity levels and the ability to carry out day-to-day tasks. "We found that OCR SNPs on Chromosome 6 were not only in strong LD with schizophrenia and bipolar disorder GWAS index SNPs, but also with the most significant eQTL for three transcripts of the BTN2A1, ZSCAN12P1, and H4C13 genes (r2 with the top eQTL of between .88 and 1) in fetal brain." (PMID 34632689, 2021).
H4C13 also shares sentences with these, for which no sentence is quoted: schizophrenia (1 paper); systemic lupus erythematosus (1).